RN7SKP53 (RN7SK pseudogene 53)
Gene: Miscellaneous RNA gene on chromosome 11 (99,120,176 to 99,120,490, forward strand). Ensembl gene ENSG00000223269.
Homologues: Orthologues: chimpanzee 7SK (97% identical), mouse Gm55992 (55% identical), mouse Gm54631 (49% identical). Paralogues in human: RN7SKP50 (66% identical), RN7SKP8 (65% identical), RN7SKP171 (65% identical), RN7SKP71 (64% identical), RN7SKP204 (64% identical), 7SK (64% identical), RN7SKP176 (64% identical), RN7SKP189 (64% identical), RN7SKP1 (63% identical), RN7SKP203 (63% identical), RN7SKP240 (63% identical), RN7SKP37 (63% identical), and 284 more.